HDAC1 (histone deacetylase 1)
Diseases named in the same sentence as HDAC1 in open-access papers (continued):
Sharing a sentence is not in itself a finding about the gene and the disease.
glioma (continued). "We detected the mRNA levels of HDAC1 using high-throughput RNA-sequencing data from the GBM cohort of TCGA and observed increased HDAC1 expression in glioma tissues compared with normal brain tissues." (PMID 28624794, 2017). "A recent study has indicated that the nuclear BNIP3 forms a complex with histone deacetylase 1 (HDAC1) and PTB-associating splicing factor (PSF) to down-regulate AIF expression in glioma cells, leading to their resistance to temozolomide-induced cell death." (PMID 28977881, 2017). "To investigate the role of HDAC1 in glioma cell lines, we measured the expression of HDAC1 in five glioblastoma cell lines using RT-PCR and Western blot assay." (PMID 28624794, 2017). "According to immunohistochemistry staining results, all 105 glioma tissue samples were divided into two groups: higher HDAC1 expression and lower HDAC1 expression." (PMID 28624794, 2017). "Although high expression and prognostic value of histone deacetylase 1 (HDAC1) have been recently reported in various types of human tumors, the molecular mechanism underlying the biological function of HDAC1 in glioma is still unclear." (PMID 28624794, 2017). "In the present study, we demonstrated that overexpression of HDAC1 in human glioma tissues and cell lines was associated with advanced WHO grade, low index of MIB (%) and poor prognosis of glioma patients." (PMID 28624794, 2017). "The data suggest that the activation of HDAC1 is a checkpoint of the development of radioresistance in glioma cells." (PMID 26521947, 2015). "Since butyrate is an inhibitor of HDAC1, the presence of butyrate in the prevention of radioresistance in glioma cells should be the effect of HDAC1-inhibition." (PMID 26521947, 2015). "The data showed that after repeated exposures to small doses of irradiation, the apoptotic glioma cells were reduced markedly as compared to control glioma cells, accompanying the increases in HDAC1 phosphorylation, in which Trib1 was required." (PMID 26521947, 2015). "The presence of HDAC1 inhibitor, butyrate or parthenolide, significantly enforced irradiation-induced glioma cell apoptosis." (PMID 26521947, 2015). "Gliomas also exhibit a significantly higher expression of HDAC1." (PMID 40581884, 2025). "Notably, HDAC1 has emerged as a key prognostic marker in glioma and is increasingly scrutinized for its potential role in immune evasion, particularly in TNBC." (PMID 40475010, 2025). "HDAC1/2/6/Sp1 activation is bound up with poor prognosis in suffers with glioma." (PMID 39068393, 2024). "This study confirms the inhibitory effect of parthenolide on HDAC1 in glioma cells." (PMID 39595109, 2024). "Furthermore, the analysis identified histone deacetylase 1 (HDAC1) as a potential REST-related gene in the context of glioma." (PMID 38534769, 2024). "To further investigate, we explored the potential role of HDAC1 in glioma." (PMID 39595109, 2024). "Based on the existing research and our findings, we infer that HDAC1/REST interaction may participate in glioma and the mechanisms of miR-9-5p and miR-105-5p/HDAC1/REST axis in glioma are needed to be validated." (PMID 36810892, 2023). "In this regard, the selective inhibition of HDAC1, which is essential for glioma stem cell survival, was more effective than vorinostat in dysregulating cell cycle proteins, and several HDAC inhibitors displayed combinatorial effects with MEKi in promoting apoptosis." (PMID 37761989, 2023). "HDAC1/2/3/10 were strongly upregulated in 11 glioma cell lines." (PMID 35359455, 2022).
glioma (continued). "We first performed the univariate cox regression and found that the elevated expressions of HDAC7, HDAC3, and HDAC1 were associated with poor prognosis while increased expressions of HDAC6, HDAC5, HDAC4, and HDAC11 were favorable for prognosis in low-grade glioma." (PMID 36227941, 2022). "Next, the contribution of HDAC1/2/3 to the TMZ-resistance of glioma cells was determined." (PMID 35365623, 2022). "Given the intrinsic phenotypic plasticity of glioma cells, we sought to determine whether the STAT3 signaling axis could be a potential compensatory mechanism that is adopted by surviving HDAC1-deficient hGSCs." (PMID 34494550, 2021). "In addition, it remains a question to be solved regarding how HDAC1 was involved with the glioma progression and the modulation of immune infiltration in glioma." (PMID 34540896, 2021). "Surprisingly, we find that HDAC1 is the essential class I deacetylase in glioma stem cells, and its loss is not compensated for by HDAC2." (PMID 34494550, 2021). "We found that, for both genes, copy number deletions were associated with lower mRNA expression, and in gliomas without HDAC1 or SIRT2 copy number variations, patients with lower HDAC1 expression or higher SIRT2 expression showed better clinical prognosis." (PMID 33718432, 2021). "The OS analysis based on GEPIA revealed that the glioma patients with high expression levels of HDAC1 (HR:3.9, p < 0.0001), HDAC2 (HR:1.3, p = 0.024), HDAC3 (HR:4.4, p < 0.0001), and HDAC7 (HR:3.3, p < 0.0001) would face with more risks compared to the ones with low expression of these genes." (PMID 34540896, 2021). "It was tempting to speculate an optimistic future for glioma not only by implementing HDAC1 and other HDACs as prognostic biomarkers but also by targeting HDAC1 and its closely related genes." (PMID 34540896, 2021). "Furthermore, we observe that ablation of HDAC1 function in GSCs suppressed expression of key glioma stemness markers like SRY-box transcription factor 2 (SOX2), Nestin, and oligodendrocyte transcription factor 2 (OLIG2)." (PMID 34494550, 2021). "Consequently, we studied the levels of HDAC1 and HDAC6 in glioma samples of different grades and associated their expression to patient survival." (PMID 32488056, 2020). "HDAC1 expression is comparatively high with exception of renal cancer and glioma." (PMID 30691229, 2019). "This indicates that ING1 might regulate HDAC1 expression beyond an epigenetic mechanism under the context of NTZ in glioma, which should be confirmed in further studies." (PMID 30302016, 2018). "In summary, HDAC1 may therefore be considered an unfavorable progression indicator for glioma patients, and may also serve as a potential therapeutic target." (PMID 28624794, 2017). "Our data provide significant molecular insight into HDAC1 and its regulation mechanisms in gliomas." (PMID 28624794, 2017). "We found that HDAC1 was elevated in glioma tissues and cell lines." (PMID 28624794, 2017). "Moreover, gene set enrichment analysis (GSEA) using The Cancer Genome Atlas (TCGA) dataset showed that HDAC1 was positively related to apoptosis and metastasis pathways, which was further validated in glioma cell lines with HDAC1 knockdown." (PMID 28624794, 2017). "We wondered if Trib1 contributed to the HDAC1 phosphorylation in glioma cells." (PMID 26521947, 2015). "Furthermore, parthenolide also suppressed the expression of HDAC1 in glioma cells, and bioinformatics analysis suggested that this effect may be related to its ability to induce neuronal differentiation." (PMID 39595109, 2024).
glioma (continued). "Furthermore, parthenolide downregulated HDAC1 expression in glioma cells, and the bioinformatics analysis revealed a potential relationship between neuronal characteristics and low expression of HDAC1 in glioma." (PMID 39595109, 2024). "Furthermore, histone deacetylase 1 (HDAC1) was a potential REST-related gene in glioma." (PMID 36810892, 2023). "Moreover, HDAC1 had the highest mRNA expression level of all HDACs in 12 glioma cell lines." (PMID 35359455, 2022). "Furthermore, querying two publicly available databases, The Cancer Genome Atlas (TCGA) and The Repository for Molecular Brain Neoplasia Database (Rembrandt), revealed that HDAC1 expression was positively correlated with a higher grade of glioma (TCGA: n = 213; Rembrandt: n = 446)." (PMID 32938908, 2020). "Similarly, HDAC1 knockdown inhibits glioma cell proliferation and invasion and induces apoptosis." (PMID 30302016, 2018). "In the previous studies, people demonstrated that the patients with advanced stage, uncontrolled tumor cellular proliferation and poor prognosis showing an increased HDAC1 expression, indicating that HDAC1 may as a molecular biomarker play an important role in glioma patients." (PMID 28624794, 2017). "Therefore, HDAC1 may therefore be considered an oncogene and a poor indicator of development in patients with glioma, and may serve as a therapeutic target in the future." (PMID 28624794, 2017). "The exact pathway that HDAC1 may involve in gliomas remains unclear." (PMID 28624794, 2017). "In the present study, HDAC1 knockdown significantly increased the expression of BIM, BAX, cleaved CASPASE3 and E-CADHERIN, and suppressed the expression of TWIST1, SNAIL and MMP9, which could be interpreted to be pro-apoptosis and anti-invasion effects of HDAC1 shRNA in glioma cells." (PMID 28624794, 2017). "The mRNA expression of HDAC1, HDAC2, HDAC3, HDAC6 and PI3K/AKT1 was analyzed in GBM and low grade glioma tissues." (PMID 40297576, 2025). "The discovery of key prognostic genes, particularly BRCA1, HDAC1, and RANGAP1, highlights their significant impact on glioma survival." (PMID 38801243, 2024). "In this study, we presented evidence of histone deacetylase 1 (HDAC1) as a potential REST-binding protein and the REST expression-correlated gene in glioma through a series of pathway enrichment analyses." (PMID 36810892, 2023). "This study identifies HDAC1 and HDAC6 as important and drug-targetable enzymes that are necessary for growth and invasiveness in IDH1 mutant gliomas." (PMID 37528157, 2023). "Ten glioma samples (5 IDH1 wildtype and 5 IDH1 mutant) were stained for various HDAC genes using internally validated antibodies (HDAC1, HDAC2, HDAC3, HDAC4, HDAC5, HDAC6 and HDAC7) and scored by a blinded neuropathologist (AK)." (PMID 37528157, 2023). "Then, using six HDAC genes (HDAC1, HDAC3, HDAC4, HDAC5, HDAC7, and HDAC9), we established a prognostic model for glioma patients, and this prognostic model was validated in an independent cohort." (PMID 35545840, 2022). "Then, using six HDAC genes (HDAC1, HDAC3, HDAC4, HDAC5, HDAC7, and HDAC9), we established a prognostic model for glioma patients, and this prognostic model was validated in an independent cohort population." (PMID 35545840, 2022). "Hence, HDAC1 may contribute to epithelial–mesenchymal transition in glioma cells." (PMID 35359455, 2022). "HDAC1 upregulation was significantly correlated with poor OS and DFS in patients with glioma patients." (PMID 35359455, 2022). "A model based on six HDAC genes (HDAC1, HDAC3, HDAC4, HDAC5, HDAC7, and HDAC9) can predict the overall survival of glioma patients well and these genes are potential therapeutic targets." (PMID 35545840, 2022). "The Oncomine data revealed that compared with normal tissues, the HDAC1/2/3/6 transcriptional levels were significantly elevated and those of HDAC2/4/5/11 were significantly decreased in CNS cancer tissues." (PMID 35359455, 2022).
glioma (continued). "We evaluated relative mRNA expression levels of HDAC1 and HDAC2 across different grades of glioma using the The Cancer Genome Atlas (TCGA), Chinese Glioma Genome Atlas (CGGA), and Repository of Molecular Brain Neoplasia Data (REMBRANDT) databases." (PMID 34494550, 2021). "It revealed that HDAC1 and HDAC6 were significantly over-expressed and within the top 5% gene rank in glioma compared to the normal group, which was evidenced by three and two studies, respectively." (PMID 34540896, 2021). "The HDAC1 and HDAC2 comparisons in glioma, and the HDAC11 comparison in GBM, were remarkable for their significantly contrasting expression." (PMID 34540896, 2021). "Differentially expressed HDAC family members were identified with significance in ONCOMINE, namely the upregulated HDAC1 and HDAC6, as well as the downregulated HDAC4, HDAC5, and HDAC11 in glioma." (PMID 34540896, 2021). "Specifically, the mRNA level of HDAC1 (p = 1.25e−13), HDAC3 (p = 2.51e−09), HDAC7 (p = 1.43e−19), and HDAC8 (p = 3.48e−10) showed an increasing trend with glioma grade progressing." (PMID 34540896, 2021). "Of note, HDAC1 was transcriptionally regulated by the nuclear factor of activated T cell (NFAT), which played a role in glioma stem cell growth and mesenchymal transition." (PMID 34540896, 2021). "HDAC1 expression increased with WHO tumor grade, and its expression was significantly higher in grade IV (GBM) than in lower grade gliomas (P < 0.001)." (PMID 34494550, 2021). "Considering the findings from ONCOMINE, GEPIA, and CGGA, HDAC1, HDAC2, and HDAC11 were thus verified for their differential expression in glioma." (PMID 34540896, 2021). "Knockdown of HDAC1 alone results in significantly prolonged survival in a patient-derived xenograft (PDX) model and a mouse model of human glioma, and the resulting tumors exhibit a more invasive growth pattern." (PMID 34494550, 2021). "These analyses showed that high levels of HDAC1 and HDAC6 correlated with decreased survival and advanced glioma grade in Rembrandt and TCGA, as well as additional cohorts." (PMID 32488056, 2020). "However, whether the association between ING1 and HDAC1 exists in glioma, or even after NTZ treatment has not been investigated nowadays." (PMID 30302016, 2018). "Of all the genes studied, HDAC1 and HDAC3 were inverselyand significantly correlated with the survival of patients with gliomas, whenanalyzed collectively (p = 0.002 and p = 0.016 respectively)." (PMID 25791281, 2015). "Additionally, the strong nuclear expression of HDAC1, HDAC2, and NCOR2 in glioma cells, along with weak expression of NCOR1 and HDAC3, suggests a potential role for these proteins in tumor progression and as markers for patient prognosis." (PMID 40940748, 2025). "Moreover, analysis of a glioblastoma multiforme (GBM) clinical database indicated that lower expressions of HDAC1, HDAC3, and AKT1 correlated with better overall survival in glioma patients." (PMID 40297576, 2025). "Since HDAC inhibitors have been found to induce neuronal-like differentiation in glioma cells, and there are currently no reports on such effects related to the drug targets of parthenolide except HDAC1, we focused our attention on HDAC1." (PMID 39595109, 2024). "Furthermore, HDAC1 was the potential REST-binding protein and the REST expression-correlated gene in glioma." (PMID 36810892, 2023). "In another example, the mRNA level of HDAC1 was upregulated in glioma cell lines and glioma tissues compared to normal glial cell lines and non-neoplastic brain tissues." (PMID 38003512, 2023). "HDAC1/2/3/4/5/7/8/11 expression significantly varied across glioma stages, whereas HDAC6/9/10 expression did not." (PMID 35359455, 2022).
glioma (continued). "Knockdown of HDAC1 alone not only delayed tumor growth but also resulted in significantly extended overall survival in a PDX model of GBM (BT145) and in a murine model of human glioma." (PMID 34494550, 2021). "Moreover, HDAC1 expression positively correlated with neutrophil (r = 0.60, p = 2.88e-47) and CD4+ T cell infiltration (r = 0.52, p = 3.96e-35) in lower-grade glioma." (PMID 34540896, 2021). "In the signature, HDAC1 (HR:1.4938) and RBL1 (HR:1.7148) were deemed a hazard, while RUNX1T1 (HR:0.7349), FKBP3 (HR:0.6382), and PHF21A (HR:0.4956) promoted survival possibilities for glioma patients." (PMID 34540896, 2021). "The DFS-oriented study using GEPIA data showed that more transcripts of HDAC1 (HR:3.0, p < 0.0001), HDAC3 (HR:2.7, p = 2.1e−15), HDAC7 (HR:2.1, p = 3e−09), and HDAC9 (HR:1.5, p = 0.0026) accompanied with less DFS probabilities in glioma patients." (PMID 34540896, 2021). "HDAC1 was obviously increased in glioma tissues compared with normal brain tissues, at both mRNA and protein levels." (PMID 28624794, 2017). "High expression, low expression and negative expression of HDAC1 were observed in 68, 32 and 5 cases of glioma, respectively." (PMID 28624794, 2017). "Concomitant inhibition of HDAC1 and activation ofHDAC4/SIRT1 may be salutary in restraining highly aggressive tumorprogression and may improve survival time in glioma patients." (PMID 25791281, 2015). "We also identified that HDAC1 and HDAC3expression levels were negatively correlated with survival time among gliomapatients, whereas the expression of HDAC4, HDAC5, HDAC6,HDAC11 and SIRT1 was positively correlated with survival time ofpatients with gliomas." (PMID 25791281, 2015). "Among all patients studied,the expression of HDAC1 and HDAC3 was inversely correlated withsurvival, whereas the expression of HDAC4, HDAC5, HDAC6,HDAC11 and SIRT1 was significantly and positively correlated withsurvival time of patients with gliomas." (PMID 25791281, 2015). "Our data indicated that the use of an unspecific DNMT inhibitor (5aza-2deoxycytidine), a DNMT1 inhibitor (procainamide) or peptides disrupting the DNMT1/PCNA, DNMT1/EZH2, DNMT1/HDAC1, DNMT1/DNMT3b and DNMT1/HP1 interactions promoted or enhanced in vivo tumorigenesis in a mouse glioma model." (PMID 23809695, 2013). "Although high HDAC1 and HDAC2 expression is related to glioma aggressiveness and proliferation, to date, no drugs have been approved for glioblastoma treatment." (PMID 41331688, 2025). "qPCR was adopted to detect the expression of HDAC1, HDAC3, HDAC4, HDAC5, HDAC7 and HDCA9 in nontumor and glioma tissues." (PMID 35545840, 2022). "The expression levels of HDAC1, HDAC3, HDAC7, and HDAC9 were significantly elevated in the glioma patients compared with the nontumor group." (PMID 35545840, 2022). "Therefore, to exclude the potential influences of 1p/19q codeletion, we compared the mRNA expression levels of HDAC1 and SIRT2 according to CNV status, as well as the OS rates between low and high levels of HDAC1 and SIRT2 mRNA expression in gliomas without HDAC1 or SIRT2 CNVs." (PMID 33718432, 2021). "While it is known that HDAC1 and HDAC2 (class I HDACs) harbor highly specific and nonoverlapping roles in the developing brain, it is unclear whether these nonredundant functions are retained in glioma cells." (PMID 34494550, 2021).